EGFR (epidermal growth factor receptor)
Diseases named in the same sentence as EGFR in open-access papers (continued):
Sharing a sentence is not in itself a finding about the gene and the disease.
cancer (continued). "The epidermal growth factor receptor, or EGFR, is a transmembrane receptor tyrosine kinase (RTK), that like many other RTKs, is commonly mutated in cancer." (PMID 38548752, 2024). "It has been noted from earlier studies that overactivation of EGFR is one of the common events that is witnessed in various types of human cancers." (PMID 38532948, 2024). "Based on these studies, the anti-EGFR antibody cetuximab has been FDA-approved for the treatment of cancers overexpressing the receptors." (PMID 38892434, 2024). "Hyperactivation of the EGFR signaling pathway contributes to MDR by promoting cancer cell proliferation and inhibiting apoptosis." (PMID 38960034, 2024). "From a theoretical standpoint, the binding energy of cancer-related proteins with CBHQs and PIBHQs was found to be generally higher for kinases such as EGFR, MEK1, and c-MET, with ΔGbin values ranging from −11.4 to −8.5 kcal/mol." (PMID 39000394, 2024). "The current study aims to investigate the anti-cancer activity of piperlongumine as a monotherapy and in combination with EGFR-TKIs or cisplatin against NSCLC." (PMID 39449797, 2024). "It specifically targets the human epidermal growth factor receptor (EGFR), which is overexpressed in many types of cancers." (PMID 39763648, 2024). "In cancer research, higher levels of glucose have been shown to increase EGFR/Stat signaling, thereby upregulating the expression of genes involved in pro-mitogenic activities." (PMID 38862239, 2024). "The advent of EGFR inhibitors has revolutionized the therapeutic landscape for various cancers, particularly in the case of NSCLC." (PMID 38611728, 2024). "Compound I and compound II revealed antibreast cancer effects related to EGFR (IC50= 0.06 μM) and HER2 inhibition (IC50= 0.18 μM), respectively." (PMID 39780846, 2024). "TKIs targeting mutated EGFR have shown superior efficacy compared to chemotherapy in treating patients with EGFR-positive cancer and have become the standard of care." (PMID 38956591, 2024). "Conversely, no differential benefit with EGFR inhibitors has been observed in Asian patients with EGFR-mutant cancer compared to non-Asians56, which is consistent with a more conserved co-alteration landscape in EGFR-mutant non-Sq NSCLC across ancestries." (PMID 39033203, 2024). "Cancer cells express proteins such as sortilin, tribbles homolog 3 protein (TRIB3), and ubiquitin specific peptidase 22 (USP22), which suppress EGFR degradation via EGFR stabilization, and their knockdown inhibits cancer cells." (PMID 38745775, 2024). "To date, several drugs targeting EGFR and its downstream signalling have been applied to treat cancer, including erlotinib, cetuximab, panitumumab and gefitinib." (PMID 39199664, 2024). "EGFR overexpression can regulate several downstream cancer promoting signaling pathways, including the PI3K/AKT pathway." (PMID 38706904, 2024). "There are several bispecific antibodies being developed for HER2- or EGFR-overexpressing cancers, which occurs in up to 40% and 74% of mUC, respectively." (PMID 38254823, 2024). "Inhibitors of Epidermal growth factor receptor tyrosine kinase (EGFR-TKIs) are producing impressive benefits to responsive types of cancers but challenged with drug resistances." (PMID 38460944, 2024). "Epidermal growth factor receptor (EGFR) mutations are found in approximately 20 to 40% of these NSCLC patients and promote cancer progression." (PMID 38581057, 2024). "Given the significance of these pathways in cancer cell survival, EGFR stands as a valuable target in treating many types of cancers, such as lung, breast, kidney, and colorectal carcinoma metastases." (PMID 39194519, 2024). "Studies conducted using the H596 NSCLC xenograft model have indicated that combining ficlatuzumab with epidermal growth factor receptor (EGFR) inhibitors such as erlotinib or cetuximab enhances its anti-cancer effects compared to using either agent alone." (PMID 39664377, 2024).
cancer (continued). "While regulators of the MAPKC, such as EGFR and KRAS, are commonly altered in cancer, mutations of MAPKs are rarely observed in cancer patients." (PMID 39062063, 2024). "The reviewed articles provide detailed information on the structural features of potent anticancer agents and their specific activity, which refers to their ability to selectively inhibit cancer-promoting kinases including CDKs and EGFR." (PMID 39404419, 2024). "Multivalent rhamnose(Rha)‐7D12 conjugates are developed to investigate the recruitment of anti‐Rha antibody capability and the induction of Fc‐mediated immunity against EGFR‐positive cancer cells." (PMID 38286668, 2024). "Overexpression of the epidermal growth factor receptor (EGFR) has been implicated in numerous types of cancers, and inhibition of its activity has shown effectiveness in treating various cancers." (PMID 38794187, 2024). "EGFR, the receptor of TGFα, is highly expressed in ESCA, which is known to be associated with the poor prognosis of a cancer." (PMID 39796131, 2024). "Examples include the therapeutic inhibition of the epidermal growth factor receptor (EGFR) signalling cascade in cancer or the development of anti-coagulant drugs targeting the blood coagulation network." (PMID 38315738, 2024). "The EGFR-dependent signaling pathway maintains cell proliferation, and its dysregulation increases cancer cell proliferation." (PMID 39048965, 2024). "EGFR amplification is also broadly observed across cancer types, including 60–80% of colorectal cancers (CRCs)." (PMID 39065587, 2024). "Precultured with OVA, modified DEXs activated T cells via MHC-antigen peptide complexes and CD86 costimulatory molecules and acted as a bridge between cancer cells and T cells by simultaneously targeting T cell surface CD3 and EGFR on cancer cells." (PMID 38172594, 2024). "This was shown to increase the sensitivity of cancer cells to conventional anti-cancer agents, especially, malignant cells harboring mutant forms of EGFR, which are often dependent on HSP90 for their stability." (PMID 39564119, 2024). "The structures and the IC50 values against a panel of cancer cell lines and EGFR subtypes for the most active agents of indole-based derivatives." (PMID 39404419, 2024). "This study aims to synthesize an anti-epidermal growth factor receptor (EGFR)-conjugated MPB (anti-EGFR-MPB) composite for cancer treatment, integrating targeted dual image-guided phototherapy and precision medicine." (PMID 39525484, 2024). "In cancers such as NSCLC, EGFR and ERBB2 are highly co-expressed and approximately 10–15% of patients developing resistance to EGFR-targeted therapies exhibit ERBB2 mutations." (PMID 38713378, 2024). "Through its biomimetic design, the nanocomposite achieves precise cancer cell targeting via anti-EGFR conjugation, while dual-modality imaging enables real-time treatment visualization." (PMID 39525484, 2024). "Meanwhile, MTOR was found to be linked to PIK3C; BRAF and MAPK1 were found to be linked to EGFR; and ERBB2 and ALK are linked to the common NSCLC and Cancer pathway." (PMID 38921583, 2024). "The epidermal growth factor receptor (EGFR), a transmembrane tyrosine kinase protein, is crucial in controlling cell proliferation and is implicated in various cancers." (PMID 38854531, 2024). "We believe the zipper mechanism in the HepG2 is due to the over-expression of epidermal growth factor receptor (EGFR) in this kind of cancer cell, which is the receptor for one of the outer membrane proteins, Rck." (PMID 39201742, 2024). "The ATP binding site, a target for two generations of FDA-approved ATP-competitive inhibitors for cancer treatment, involves key residues such as Thr790, Met793, and Cys797 for drug-EGFR interactions." (PMID 38751788, 2024). "The inhibition of this signaling provides a clinical rationale for using anti-EGFR/NF-κB co-treatment to fight residual cancer and re-sensitize cancer patient response." (PMID 37789138, 2024).
cancer (continued). "EGFR overexpression has also been used to enable specific binding of functionalized UNPs (anti-EGFR-UNPs) for imaging modalities to achieve three-dimensional functional tissue imaging based on laser scanning in cancer cells." (PMID 38334567, 2024). "There was a significant enrichment of YAP-associated transcripts in DTPs across EGFR-mutant, ALK fusion-positive, and KRAS-mutant cancer cell." (PMID 38702301, 2024). "What percentage of patients with EGFR-driven cancer would benefit from a preemptive combination like Osimertinib, afatinib, and capmatinib?" (PMID 38497774, 2024). "It has been discovered that the USP43/NuRD complex inhibits the expression of numerous cancer-related genes, including the epidermal growth factor receptor (EGFR)." (PMID 38613804, 2024). "PKB is often activated in cancer cells via the dysregulation of upstream signaling pathways, such as growth factor receptors like EGFR and PDGFR." (PMID 38474118, 2024). "The PI3K/AKT/mTOR signaling pathway is activated by EGFR and has a role in cancer cell growth and resistance in CCA to chemotherapy." (PMID 38339363, 2024). "Such aberrant EGFR activity is characteristic of numerous cancer types, including lung, breast, and colorectal cancers." (PMID 38474160, 2024). "Mutations in the EGFR gene result in the higher expression of EGFR proteins in certain types of cancer cells and transportation of EGFR via EVs induces an accelerated progression of cancer cells." (PMID 39611045, 2024). "The presence of multiple distinct primary EGFR-mutant cancers at the time of clinical presentation has long represented a conundrum." (PMID 39406916, 2024). "The 99 KEGG pathways were enriched, such as microRNAs in cancer, focal adhesion, epidermal growth factor receptor (EGFR) tyrosine kinase inhibitor resistance." (PMID 39029056, 2024). "When inserting the adapter A2 between the RIP saporin and the targeting moiety EGF (Saporin-A2-EGF), an improved anti-cancer effect in mice with EGFR-positive tumors and simultaneously lesser side effects were observed in comparison to Saporin-EGF." (PMID 38685061, 2024). "Human epidermal growth factor receptor (EGFR) plays a pivotal role in cell growth and is highly expressed in cancer cells." (PMID 39273378, 2024). "This nanobody has been explored for various applications in cancer diagnosis, imaging, and therapy due to its high specificity and affinity for EGFR." (PMID 39763648, 2024). "Tandyukisin demonstrated significant inhibitory activity against cancer cells expressing high levels of EGFR, while exhibiting negligible inhibitory effects on both low EGFR-expressing cancer cells and normal human breast cells." (PMID 38751788, 2024). "Recent investigations have unveiled the promise of chemicals targeting dysregulated EGFR and its regulators as an alternative approach to combating cancer, a potential primarily attributed to their capacity to thwart multiple signaling pathways." (PMID 39124760, 2024). "Increasing evidence suggest that EMT is a critical contributor to cancer metastasis and drug resistance, including that to EGFR-TKIs." (PMID 38872157, 2024). "Targeted therapies are designed to specifically interact with molecular alterations—such as mutations in EGFR and ALK genes—that promote cancer cell growth and survival." (PMID 39682234, 2024). "The epidermal growth factor receptor (EGFR) was identified as a potential therapeutic target in the fight against cancer more than 20 years ago." (PMID 38402342, 2024). "In preclinical studies, gefitinib showed anticancer effects against several human cancer cell lines expressing EGFR (e.g., lung, ovarian, breast and colon cancers)." (PMID 38338677, 2024).
cancer (continued). "EVs quantification of the active EGFR+ EVs in untreated plasma demonstrated that the biosensor is excellent for the detection of specific types of cancer." (PMID 38830977, 2024). "This review highlighted the progress in targeting CDKs and EGFR as promising strategies in cancer therapy." (PMID 39404419, 2024). "The study highlights the importance of CD133, a cancer stem cell marker, and the EGFR and VEGF signaling pathways in this GBM mouse model." (PMID 38473403, 2024). "Loss of lineage-specific expression of MEP LRPs with age was associated with (i) pathways involved in cancer; (ii) pathways involved with MAPK, EGFR, NOTCH, and PI3K-AKT signaling; and (iii) MEP contractility." (PMID 39545637, 2024). "DOCK4 is crucial for cancer cell extravasation to the brain, with EGFR activation driving cell elongation reversed by Afatinib." (PMID 38762624, 2024). "Polyphenolic compounds primarily modulate PD-L1 expression by inhibiting key signaling pathways (IFN-γ-induced STAT1, STAT3, JAK2/STAT1, EGFR/Akt, and NF-κB), potentially enhancing the immune system’s capacity to target and eradicate cancer cells." (PMID 38594256, 2024). "The epidermal growth factor receptor (EGFR or HER1) is a membrane protein that is highly overexpressed in cancer." (PMID 38543324, 2024). "In this way, CD24 indirectly facilitates cancer cell metastasis by triggering the EGFR, ERK1/2, and Akt signaling pathways." (PMID 38881902, 2024). "Antibody-mediated strategies involve engineering EV surfaces with anti-CD3 and anti-EGFR antibodies, leading to the T-cell-mediated elimination of EGFR-positive cancer cells." (PMID 38893088, 2024). "In this comprehensive review, we provide a thorough summary of the current literature concerning the utilization of radiolabeled EGFR- and integrin αVβ3-targeting peptides in cancer imaging and peptide receptor radionuclide therapy (PRRT)." (PMID 39126121, 2024). "In cancer, EGFR frequently undergoes alterations, leading to abnormal signaling that promotes cancer cell survival and proliferation." (PMID 38689087, 2024). "The small GTPase KRAS is a well-characterized oncoprotein that increases the malignancy and metastatic potential of cancer cells by acting as an epidermal growth factor receptor (EGFR) signaling transducer." (PMID 38532366, 2024). "To date, many different small molecules have been developed as potential EGFR TKIs, from first to fourth generation, some of which are used in the clinical treatment of cancer." (PMID 39054543, 2024). "The first-in-human phase 1 study (NCT01287546) evaluated emibetuzumab monotherapy versus emibetuzumab plus erlotinib (an EGFR TKI) in patients with advanced cancer (NSCLC specifically: n = 4 versus 14, respectively)." (PMID 39449330, 2024). "IgTT-4E1-S enhanced the activation and effector functions of human primary T cells co-cultured with EGFR+/PD-L1+ cancer cells." (PMID 38804302, 2024). "The KEGG pathway indicated that the differentially expressed proteins were mainly involved in EGFR tyrosine kinase inhibitor resistance, FoxO signaling central carbon metabolism in cancer, and the mTOR signaling pathway." (PMID 39335579, 2024). "The pattern regarding prior cancer treatment was similar to the group starting treatment with an EGFR inhibitor." (PMID 39693368, 2024). "EGFR overexpression can lead to cancer by making cancer cells more resistant to apoptosis (programmed cell death) and more likely to metastasize." (PMID 39453005, 2024). "The dependency on EGFR for cancer survival, which is a key determinant of EGFRi sensitivity, is also measurable using the Project Achilles dataset based on cell viability data following genetic perturbation." (PMID 38551001, 2024). "Our findings unravel the significance of impairing antioxidant defense in EGFR-driven cancer and repurposing auranofin and L-BSO treatment to improve the dismal survival of patients with GBM." (PMID 39001381, 2024).
cancer (continued). "EGFR, or Epidermal Growth Factor Receptor, is a cell surface signaling protein that plays a significant role in many types of human carcinomas." (PMID 38881902, 2024). "On the other hand, EGFR was overexpressed in many epithelial carcinomas including HNCs, which exhibited EGFR overexpression in up to 90% of tumors." (PMID 39684225, 2024). "Epidermal growth factor receptor (EGFR) is a receptor tyrosine kinase (RTK) that is overexpressed, mutated or otherwise dysregulated in a large fraction of human cancers." (PMID 37169593, 2023). "Current treatments for these types of cancers include tyrosine kinase inhibitors (TKIs), which inhibit downstream signaling by directly impairing EGFR tyrosine kinase activity." (PMID 37752992, 2023). "EGFR is overexpressed in several types of cancers and is considered a potential target for cancer therapy." (PMID 37243023, 2023). "Since EGFR and mTORC1 drive central mitogenic pathways in the cell and are frequently hyperactivated in human cancers, it is likely that their concomitant inhibition by THZ531 causes the strong repression of proliferation observed in our study." (PMID 37202753, 2023). "Afatinib, a dual inhibitor of HER2 and EGFR, showed a promising effect on cancers with amplified HER2 E401G, which have an EGFR-mediated activation mechanism." (PMID 36690964, 2023). "To explore the role of EGFR signaling in chemotherapy-induced resistance to ferroptosis, we combined low-dose Oxaliplatin and the EGFR monoclonal antibody Cetuximab to treat cancer cells." (PMID 37253718, 2023). "Evidences for the role of EGFR in inhibition and pathogenesis of various cancers have led to the development of agents that target this receptor." (PMID 37660139, 2023). "Nine compound candidates were identified, which have been showed to reduce EGFR expression in cancer cells and were reproduced in at least two literatures." (PMID 37178919, 2023). "Our study revealed the therapeutic potential of our modified CAR-T cells against EGFR-positive human cancers such as NSCLC." (PMID 36982500, 2023). "Gefitinib is a tyrosine kinase domain inhibitor of the epidermal growth factor receptor (EGFR), which prevents signaling in target cancer cells with mutant and excessive EGFR." (PMID 38139840, 2023). "In other words, even in the cancer cells that are innately resistant to EGFR kinase inhibitors, EGFR is indispensable for survival." (PMID 37446288, 2023). "EGFR is often recorded in pathology reports due to its increasing use as a prognostic indicator, highlighting its importance in the progression of cancer." (PMID 37232831, 2023). "As EGFR is extensively expressed in numerous cancers, nanobody-based anti-EGFR PDT has been fully explored." (PMID 38067344, 2023). "One such example is 99mTc, a radio-labeled, anti-epidermal growth factor receptor (EGFR) nanobody that can detect EGFR-expressing cancer cells with higher accuracy and visualization." (PMID 36835588, 2023). "Multiple oncogenic signaling cascades (EGFR, CXCR4, FASN, P-gp, β-catenin, GSK-3B, STAT1, JAK2, MUC1, etc) are hallmarks of cancer cells that are associated with drug resistance, tumorigenic potential, and metastasis." (PMID 37151801, 2023). "A SNP near the intron/exon boundary of exon 7 in epidermal growth factor receptor (EGFR) – involved in controlling cell proliferation, whose alterations are frequent in different cancer types, increases the risk of developing GBM." (PMID 37400829, 2023). "(−)-Epigallocatechin-3-gallate (EGCG) is one of the most abundant and biologically active molecules in green tea; it acts as a tyrosine kinase inhibitor towards cancer cells overexpressing EGFR." (PMID 37762316, 2023). "Cetuximab is frequently used as a vehicle and in combination treatments to enhance the therapeutic efficacy of EGFR-targeted cancer treatment." (PMID 37438719, 2023).